PAXBP1 (PAX3 and PAX7 binding protein 1)
Description:
Adapter protein linking the transcription factors PAX3 and PAX7 to the histone methylation machinery and involved in myogenesis. Associates with a histone methyltransferase complex that specifically mediates dimethylation and trimethylation of 'Lys-4' of histone H3. Mediates the recruitment of that complex to the transcription factors PAX3 and PAX7 on chromatin to regulate the expression of genes involved in muscle progenitor cells proliferation including ID3 and CDC20.
Synonyms: C21orf66; GCFC; GCFC1; fSAP105; BM020
Tractability: Small molecule: a structure with a bound ligand is known. PROTAC: UniProt records ubiquitination sites on it; ubiquitination databases record sites on it; its protein half-life has been measured.
Gene: Protein-coding gene on chromosome 21 (32,733,899 to 32,771,796, reverse strand). Ensembl gene ENSG00000159086.
Subcellular location: Nucleus
Subcellular location (Human Protein Atlas): Nucleoplasm; Cytosol
Gene Ontology:
Molecular function: DNA binding; histone methyltransferase binding
Biological process: positive regulation of transcription by RNA polymerase II; mRNA splicing, via spliceosome
Cellular component: cytosol; nucleus
Genetic constraint (gnomAD): Loss-of-function variants: 33 observed, 99.54 expected, observed/expected ratio (o/e) 0.33, 90% interval 0.25 to 0.44. The upper end of that interval is the gene's LOEUF score, 0.44, which puts it in group 1 of 6, group 1 being the genes least tolerant of losing a copy. Missense variants: 841 observed, 1,003.6 expected, observed/expected ratio (o/e) 0.84, 90% interval 0.79 to 0.89. Synonymous variants: 369 observed, 356.66 expected, observed/expected ratio (o/e) 1.03, 90% interval 0.95 to 1.13.
Homologues: Orthologues: chimpanzee PAXBP1 (99% identical), macaque PAXBP1 (99% identical), pig PAXBP1 (97% identical), mouse Paxbp1 (95% identical), guinea pig PAXBP1 (95% identical), rat Paxbp1 (95% identical), tropical clawed frog paxbp1 (72% identical), zebrafish paxbp1 (57% identical), Drosophila melanogaster CG1965 (30% identical), Caenorhabditis elegans mog-7 (23% identical). Paralogues in human: GCFC2 (28% identical).
Diseases named in the same sentence as PAXBP1 in open-access papers:
PAXBP1 is named in the same sentence as 7 diseases in open-access papers, as found by Europe PMC text mining. Sharing a sentence is not in itself a finding about the gene and the disease. The quoted sentences say what the papers report.
Atrophy (1 paper, 2023). Any weakening or degeneration, especially through lack of use. "Here, we observed that deletion of Paxbp1 resulted in thymic atrophy in mice lacking Paxbp1 in the early stages of T cell development." (PMID 37404821, 2023).
Crohn disease (1 paper, 2023). A gastrointestinal disorder characterized by chronic inflammation involving all layers of the intestinal wall, noncaseating granulomas affecting the intestinal wall and regional lymph nodes, and transmural fibrosis. "NCOR2, NFATC4 and PAXBP1 code for transcription-associated factors and their dysregulations are linked to Crohn's disease, carcinogenesis and myopathic hypotonia, respectively." (PMID 37026480, 2023).
lymphopenia (1 paper, 2023). Reduction in the number of lymphocytes. "Taken together, these findings reveal that poor thymocyte formation in Paxbp1 cKO mice leads to peripheral lymphopenia." (PMID 37404821, 2023).
microcephaly (1 paper, 2025). A congenital or acquired developmental disorder in which the circumference of the head is smaller than normal for the person's age and sex. "This variant was identified in 2 patients with microcephaly, but the symptoms could not be specifically attributed to the EXOSC4 variant because the patients also had a pathogenic variant in another protein, PAXBP1, that appears to explain the disease." (PMID 39982806, 2025).
thymic atrophy (1 paper, 2023). "Here, we found that Lck-cre-mediated T cell-specific loss of Paxbp1 (abbreviated as Paxbp1 cKO) resulted in thymic atrophy and significant reductions in the numbers of DP cells, CD4+ SP, and CD8+ SP cells in the thymus, and fewer T cells in the periphery." (PMID 37404821, 2023).
PAXBP1 also shares sentences with these, for which no sentence is quoted: COVID-19 (1 paper); developmental delay (1).